MIR4323 (microRNA 4323)
Synonyms: hsa-mir-4323
Gene: MicroRNA gene on chromosome 19 (42,133,445 to 42,133,513, reverse strand). Ensembl gene ENSG00000266226.
Homologues: Orthologues: chimpanzee MIR4323 (100% identical).